LINC00570 (long independently transcribed non-coding RNA 570)
Synonyms: ncRNA-a5
Gene: Long non-coding RNA gene on chromosome 2 (11,371,440 to 11,407,023, forward strand). Ensembl gene ENSG00000224177.
Diseases named in the same sentence as LINC00570 in open-access papers:
LINC00570 is named in the same sentence as 3 diseases in open-access papers, as found by Europe PMC text mining. Sharing a sentence is not in itself a finding about the gene and the disease. The quoted sentences say what the papers report.
cervical carcinoma (1 paper, 2021). A carcinoma arising from either the exocervical squamous epithelium or the endocervical glandular epithelium. "We used RNA-sequencing data to search for cell models where LINC00570 is expressed, and identified robust expression in cervical carcinoma HeLa cells." (PMID 34316704, 2021).
cancer (1 paper, 2021). A tumor composed of atypical neoplastic, often pleomorphic cells that invade other tissues. "In summary, LINC00570 predicted by CLIO-TIM pipeline promotes growth of human cancer cells, and is likely to have a deeply evolutionarily conserved tumorigenic activity." (PMID 34316704, 2021). "To experimentally test the principal that human orthologues of mouse cancer genes have a conserved function, we selected LINC00570, identified by CLIO-TIM but never previously been linked to cancer or cell proliferation." (PMID 34316704, 2021).
cardiovascular disease (1 paper, 2021). "However, to the best of our knowledge, the role of LINC00570 is yet to be reported in cardiovascular disease." (PMID 34753383, 2021).